LHB (luteinizing hormone subunit beta)
Diseases named in the same sentence as LHB in open-access papers (continued):
Sharing a sentence is not in itself a finding about the gene and the disease.
Anxiety (continued). "The LHb regulates anxiety-related behaviors through its complex connection with distal regions." (PMID 35145415, 2022). "Thus, the aim of the present study was to investigate the effects of activating and blocking LHb AMPARs on anxiety-like behaviors and changes of dopamine (DA) and serotonin (5-HT) release in the ipsilateral basolateral nucleus of BLA." (PMID 35145415, 2022). "Thus, we chose the 21-day time point for subsequent experiments when investigating the role of the LHb in generating the anxiety-like behaviors induced by pT-ION." (PMID 36187288, 2022). "Moreover, blocking glutamate transmission or LHb neuronal activity rescued anxiety-like behaviors in alcohol-depriving rats and suppressed alcohol intake upon the reexposure to alcohol." (PMID 35145415, 2022). "In addition to the increase and decrease in anxiety-like behaviors demonstrated here by (S)-AMPA and NBQX, respectively, these findings support a role for LHb AMPARs in mediating anxiety via its effects on DA and 5-HT in the BLA." (PMID 35145415, 2022). "The activation of CaMKII+ neurons in the bilateral LHb may induce pain and anxiety via LHb regulation of the 5-HT, dopaminergic, and overall reward systems given its complex network of nerve projections." (PMID 36187288, 2022). "DPN may inhibit LHb activity to improve anxiety-like behavior in OVX rats by increasing monoamine neurotransmitter levels in the DRN and VTA." (PMID 35615566, 2022). "Together, these studies suggest that LHb neurons may be activated in an estrogen reduction-induced anxiety state." (PMID 35615566, 2022). "The effect of chronic nicotine on the LHb neuronal firing is unknown, although we have shown that chronic nicotine treatment induced an effect similar to the LHb lesion on the anxiety-like behavior of rats." (PMID 33946328, 2021). "The LHb has also been indicated as a hub for nicotine effects, i.e., nicotine excites LHb neurons in vivo and in vitro and acute and chronic nicotine-induced anxiety is counteracted by LHb lesion." (PMID 33946328, 2021). "On the other hand, the LHb has been shown to be a critical node in the pathophysiology of anxiety." (PMID 32264959, 2020). "Moreover, the LHb was reported to be activated and to contribute to the induction of anxiety-like behaviors in temporomandibular disorders, which are dysfunctions of the orofacial region." (PMID 32264959, 2020). "The lateral habenula (LHb) is considered to be involved in the modulation of pain and mood disorders, and the present study aimed to determine if and how the LHb participates in the development of pain and anxiety in TN." (PMID 32264959, 2020). "In light of these previous studies and our own observations, we hypothesize that UAC, as an unpleasant external stimulation, generates anxiety mediated by the LHb." (PMID 31427925, 2019). "Concurrently, different types of LHb inactivation/lesion, which might potentially produce control animals with lower levels of basal anxiety compared to those used in our current study, should be considered." (PMID 26082682, 2015). "Recent analyses suggest that the LHb may play a crucial role in suppressing locomotor activity when an aversive outcome is anticipated or when pain, stress or anxiety is experienced." (PMID 23922655, 2013). "In addition, to determine whether mice with activation of LHb neurons exhibited anxiety-like behaviors, the mice were subjected to the EPM and OFT after CNO administration." (PMID 36756128, 2023). "However, whether the activation of LHb neurons in normal naïve mice has any effects on sensory conduction and anxiety has remained unknown." (PMID 36756128, 2023). "Increasing studies suggest that the LHb is highly involved in the regulation of anxiety-like behaviors; for example, the rats refraining from chronic excessive alcohol consumption showed an anxiety-like phenotype, an increase in glutamate release, and hyperactivity of LHb neurons." (PMID 35145415, 2022).
Anxiety (continued). "Therefore, we hypothesized that OVX-induced anxiety-like behavior may be attributed to increased neuronal activity of the LHb, leading to reduced neuronal activity of the DRN and VTA, which reduces the release of 5-HT and DA neurotransmitters." (PMID 35615566, 2022). "However, whether and how the LHb participates in the pathogenesis of pain and anxiety in TN is unknown." (PMID 32264959, 2020). "Therefore, nerve injury-induced allodynia and anxiety-like behaviors are differentially modulated by the LHb, and selective inhibition of unilateral or bilateral LHb function by Tacr3-targeting methods is a promising treatment for pain and anxiety in TN patients." (PMID 32264959, 2020). "Consequently, our results indicate that the LHb is an important area of the anxiety circuitry." (PMID 26082682, 2015). "Therefore, nicotine acting on the LHb would increase 5-HT neuronal activity and its release in several brain regions, including mPFC, hippocampus and amygdala leading to the development of an anxiety state." (PMID 26082682, 2015). "Indeed, strings and percentage of T-patterns containing edge-sniff and/or head-dipping describe, in both sham and LHb-lesioned animals, a situation essentially consistent with an increased anxiety level, although the influence of the hypolocomotion induced by surgery cannot be excluded." (PMID 26082682, 2015). "Inhibiting these postsynaptic receptors (such as through CGP35348) enhances LHb activity, reduces DA and 5-HT release in the BLA, and produces anxiety-like behaviors by observing decreased open-arm time and increased percentage of open-arm entries." (PMID 40635883, 2025). "Here, we showed that LHb neurons were also abnormally activated in pT-ION mice and that these mice had performance anxiety." (PMID 36756128, 2023). "However, it is still unclear whether LHb mediates the anti-anxiety effects of estrogen." (PMID 35615566, 2022). "(S)-AMPA injected into the LHb significantly raised anxiety-like behaviors in the OFT and EPM tests, while blockade of LHb AMPARs using NBQX produced an anxiety-like behavior in both groups and suppressed the anxiety-like phenotypes in rats." (PMID 35145415, 2022). "Activation of LHb glutamatergic input to LDT GABAergic interneurons can generate fear-like responses, and prolonged activation of interneurons in LDT can induce anxiety-like behaviors." (PMID 36386995, 2022). "Recently, an increased activity of the LHb glutamatergic neurons has also been reported after infraorbital nerve injury and chemogenetic inhibition of these neurons alleviated anxiety, but not allodynia." (PMID 36979799, 2023). "In our results, there was also inconsistency between EPM and OFT performance, and we showed that activation of bilateral LHb induced anxiety-like behaviors in the OFT but not in the EPM." (PMID 36756128, 2023). "Injection of DA receptor agonists or antagonists into LHb showed that activation or inhibition of DRD1 but not DRD2 in LHb increased anxiety-like behavior, but decreased depressive-like behavior in rats." (PMID 36059987, 2022). "These control experiments suggest that LHb inactivation (on its own) does not affect general movement, hunger, motivation to explore related to anxiety-like behavior or reward-seeking behavior." (PMID 33712440, 2021). "We found that LHb pharmacological inactivation did not affect cued threat conditioning (fear) and extinction (safety) learning and memory, anxiety-like or reward-seeking behaviors." (PMID 33712440, 2021). "Here we explore whether optogenetic silencing of the LHb only during the tailshock intervals of IS prevents the increases in BLA extracellular 5-HT during IS, as well as increased BLA 5-HT and anxiety-like behavior during JSI 24 h later." (PMID 27785462, 2016).
Anxiety (continued). "Overall, these experiments highlight a critical role for LHb in driving DRN activation and 5-HT release into downstream circuits that mediate anxiety-like behavioral outcomes of IS and further support the idea that behavioral control does not modulate excitatory inputs to the DRN." (PMID 27785462, 2016). "The LHb lesion might produce some neurochemical (i.e., DA, 5-HT, glutamate, GABA) or hormonal (e.g., corticosterone) changes which indirectly antagonize the anxiety state induced by nicotine treatment." (PMID 26082682, 2015). "As of yet, no data exist regarding the involvement of the LHb in nicotine-induced anxiety-like behavior in animals." (PMID 26082682, 2015). "Therefore, selective inhibition of LHb function by targeting NMDA/CaMKII signaling may represent a therapeutic approach to pain and related experiences of anxiety in patients with TN." (PMID 36187288, 2022). "However, our data do not allow us to be conclusive about the role of the LHb in general and nicotine-induced anxiety-like behavior." (PMID 26082682, 2015). "Hence, the LHb might also be a key area of interest in nicotine-induced anxiety, although this hypothesis has not been investigated to date." (PMID 26082682, 2015).
mood disorder (9 papers, 2017 to 2024). A cognitive disorder a disturbance in which the person's mood is hypothesized to be the main underlying feature. "LHb is involved in cognition and mood disorders via modulation of downstream serotonergic and dopaminergic centers." (PMID 36685083, 2022). "For example, studies in rodents reveal that shifted glutamate/GABA co-transmission appear in altered LHb circuits in mood disorders." (PMID 36685083, 2022). "It has been shown that the LHb participates in the modulation of both pain and mood disorders and that removal of the LHb reduces both pain and mood disorders." (PMID 32264959, 2020). "This can be obtained, for instance, by performing double-blind studies on a much larger cohort of patients to properly evaluate the clinical utility of LHb targeting in mood disorders." (PMID 30083090, 2018). "Additionally, due to the LHb’s involvement in addiction, mood disorders, and schizophrenia, understanding the influence of BF circuitry on this aversion node can potentially aid in our understanding of other types of mental illnesses." (PMID 36543829, 2022). "Thus, we predict that stress-induced pathophysiological firing in the putative loop consisting of the LHb, DRN, and SCN (LHb→DRN→SCN→LHb) may be responsible for changes in daily rhythms associated with mood disorders." (PMID 33690628, 2021). "In addition to contributing to these mood disorders, because down-regulated MHb cholinergic signaling is involved in anhedonia-like behavior, the MHb–IPN cholinergic circuit represents an alternative pathway to the LHb–VTA circuit for regulating hedonic state." (PMID 28420875, 2017).
Infertility (8 papers, 2010 to 2026). "Loss-of-function variants in FSHB and LHB have been associated with infertility, primary amenorrhoea, azoospermia and variable impairment of pubertal development." (PMID 36517585, 2023). "In women, some other LHB SNPs were associated with infertility or central precocious puberty." (PMID 40001128, 2025). "The mutations at the SNPs of TEX11 (rs4844247), LHB (rs4146251380), USP26 (rs61741870) and (rs41299088), and ANOS1 (rs2229013) were displayed in only one of eight infertile men." (PMID 37895049, 2023). "Large fluctuations in LHB expression could lead to hypogonadism, infertility and several other endocrine disorders in both sexes as can be seen in patients with various mutations in the LHB gene." (PMID 20488225, 2010).
schizophrenia (7 papers, 2015 to 2024). A major psychotic disorder characterized by abnormalities in the perception or expression of reality. "Dysfunction of the LHb has also been involved in different cognitive disorders, such as schizophrenia and addiction." (PMID 34251338, 2021). "However, in schizophrenia, LHb activity is hypoactive, disinhibiting serotonergic activity in the DRN." (PMID 35444521, 2022). "Owing to these findings, hypofunction in the LHb may contribute to the pathophysiology of schizophrenia." (PMID 35444521, 2022). "Finally, we turn to human populations once more to examine how altered DA signaling and LHb dysfunction may play a role in social anhedonia, a common feature in diagnoses such as schizophrenia and major depressive disorder (MDD)." (PMID 35990728, 2022).
hypogonadism (5 papers, 2010 to 2026). A disorder characterized by decreased function of the gonads. "Furthermore, mutations in the genes ECEL1 and LHB, are associated with skeletal muscle and limb anomalies as well as hypogonadism." (PMID 36421828, 2022). "Mutation in LHB gene could causes hypogonadism, which is also manifested in individuals with TARP syndrome." (PMID 24000153, 2013).
bipolar disorder (4 papers, 2015 to 2024). A disorder of the brain that causes unusual shifts in mood, energy, activity levels and the ability to carry out day-to-day tasks. "It is unclear if the pathway making the connections between the amygdaloid complex and the GPh, LHb, RMTg, VTA, and finally the NAcbC is primary affected in such bipolar disorder or if the regulation of the LHb by the MHb is aberrant." (PMID 28588455, 2017).
cognitive deficits (4 papers, 2014 to 2025). "Together, our findings suggest that restoring the balance of LHb local network activity may be a strategy to reverse cognitive deficits observed in inflammatory pain conditions." (PMID 36979799, 2023). "Since the information processing in cortico-hippocampal areas in cognitive behaviors is influenced by various neuromodulators (including dopamine, serotonin etc.)and the release of these neuromodulators is under the control of the LHb, the dysfunction in LHb may induce the cognitive impairments." (PMID 25505877, 2014).
nicotine addiction (4 papers, 2015 to 2021). "In conclusion, our data are important in the context of the mechanisms involving the 5-HT2ARs, the LHb and other brain areas in nicotine addiction." (PMID 32182934, 2020). "Manipulating LHb activity, especially through α6*-nAChRs, may therefore be of great value in treating nicotine addiction." (PMID 27596561, 2016). "The loss of LHb feed-forward negative input to the VTA in chronic nicotine-treated maybe therefore be important for the establishment and maintenance of nicotine addiction." (PMID 33946328, 2021).
Alcohol Use Disorders (2 papers, 2020 to 2024). "Manipulating LHb function can ameliorate recurrent drinking and psychiatric disorders in abstinent animals, suggesting that alcohol use disorders are related." (PMID 39539942, 2024).
Bradycardia (2 papers, 2021 to 2024). A slower than normal heart rate (in adults, slower than 60 beats per minute). "Although we observed that electrical stimulation of the LHb induced bradycardia, a previous study reported tachycardia evoked by such stimulation." (PMID 33854416, 2021). "Therefore, the specific activation of the LHb might cause bradycardia." (PMID 33854416, 2021). "On the other hand, even when we tested to stimulate the LHb with a higher stimulation intensity (1 mA) or the same stimulation parameters with the previous report, we could observe only bradycardia but not tachycardia." (PMID 33854416, 2021).
cocaine addiction (2 papers, 2023). "As our previous studies showed that MS activates an LH–LHb pathway to inhibit the mesolimbic DA system and cocaine addiction–like behaviors, we hypothesized that the MS effects on cocaine addiction–like behaviors may be mediated via an orexinergic pathway from the LH to the LHb." (PMID 37501724, 2023).
diabetes (2 papers, 2022 to 2024). "To further determine whether LHb was the critical substrate for the alleviation of depression-like behaviors induced by diabetes, we used chemical genetic approaches to reduce the activity of LHb neurons." (PMID 38440257, 2024). "Furthermore, significant reductions in LHb activation patterns were also observed in animal models of diabetes-induced neuropathic pain and tail pinch intermittent stressor." (PMID 35819957, 2022).
memory impairment (2 papers, 2022 to 2025). "The task-specific nature of the memory impairments caused by hyperactivation of LHb glutamatergic neurons reveals another level of complexity to the role of LHb activity in memory." (PMID 40799491, 2025). "Direction inhibition or damage of the LHb or retrograde inhibition of LHb neurons via its projections to the VTA attenuated surgery‐induced learning and memory impairment." (PMID 35616407, 2022).
prostate carcinoma (2 papers, 2013 to 2022). A carcinoma that arises from epithelial cells of the prostate gland. "Studies reported that LHB is correlated with high-risk epithelial ovarian cancer and prostate cancer." (PMID 35190739, 2022). "It should be noted that the gene GSTP1 was in an association with ferritin H gene, gene LHB was significantly with testosterone and estradiol levels and special CYP3A/KLK3 genotypes increased metastatic disease while the expression of CYP3A in prostate cancer was regulated by androgen." (PMID 24146788, 2013). "Moreover, the genes GSTP1 and SLCO2B1in 11q13 as well as the genes LHB and KLK3in 19q13were reported to involve in sex hormones metabolic pathway, though the previous study showed that the latter two genes were not so significant for risk factor in prostate cancer." (PMID 24146788, 2013).
seminoma (2 papers, 2023 to 2025). A radiosensitive malignant germ cell tumor found in the testis (especially undescended), and extragonadal sites (anterior mediastinum and pineal gland). "Expression of FSHB was basically restricted to a small fraction of seminomas and LHB was strongly upregulated in seminoma as compared with NSGCT, in line with the differences in serum levels of our cohort." (PMID 37669975, 2023).
alcohol dependence (1 paper, 2021). Physical and psychological dependence on alcohol. "Additionally, we evaluated whether LHb CB1R activation changes ethanol drinking behavior and whether it is related to the state of alcohol dependence." (PMID 33854035, 2021).
attention deficit-hyperactivity disorder (1 paper, 2023). A disorder characterized by a marked pattern of inattention and/or hyperactivity-impulsivity that is inconsistent with developmental level and clearly interferes with functioning in at least two settings (e.g. at home and at school). "Indeed, a recent hypothesis has proposed that LHb hypoactivity in childhood may promote attention deficit hyperactivity disorder, which in turn primes the LHb to be more responsive to stress in adulthood." (PMID 36371544, 2023).
bipolar II disorder (1 paper, 2013). A bipolar disorder that is characterized by at least one hypomanic episode and at least one major depressive episode; with this disorder, depressive episodes are more frequent and more intense than manic episodes. "In terms of clinical typology, this resembles bipolar II disorder, which may be the patient population most likely to show LHb effects." (PMID 24133441, 2013).
chronic hepatitis B (1 paper, 2015). "Taken together, our in vitro data suggest that mutation in the LHB region, such as W4P, during the natural course of chronic hepatitis B, may contribute to HCC generation." (PMID 25645622, 2015). "Our in vivo mouse data clearly proved that W4P LHB, but not WT LHB, had higher potential for tumor formation in male than in female mice, suggesting mutations in LHB, such as W4P, occurring in a later stage of chronic hepatitis B, could contribute to the gender disparity in HCC generation." (PMID 25645622, 2015).
cocaine use disorder (1 paper, 2018). A substance-related disorder that involves the recurring use of cocaine despite negative consequences. "In addition to regulating negative RPE, the LHb is critically involved in learning and memory processes that are associated with avoidance behaviors, which are also disrupted in patients suffering from cocaine-use disorder." (PMID 29896097, 2018).